S100P (S100 calcium binding protein P)
Diseases named in the same sentence as S100P in open-access papers (continued):
Sharing a sentence is not in itself a finding about the gene and the disease.
cancer (continued). "Our qRT-PCR results also indicated that S100P was highly expressed in cancer tissues." (PMID 36338624, 2022). "Although most studies have focused on the function of S100P in malignant tumors, a relationship between S100P and calcium signaling in mammalian embryo and placental development has also been reported given that S100P promotes cell proliferation, survival, invasion and vascularization." (PMID 36187124, 2022). "Yet, the role of S100P has been mostly investigated in the context of cancer." (PMID 35317077, 2022). "S100P plays a key role in the progression of a variety of cancers." (PMID 36187124, 2022). "Furthermore, Pearson correlation analysis indicated that the expression of circ_0092314 was negatively correlated with miR-671 expression, and positively correlated with S100P mRNA expression in PAAD cancer tissues." (PMID 33842379, 2021). "S100P has also been reported to reduce apoptosis to promote cancer progression." (PMID 34215278, 2021). "S100P levels may have a predictive value of response to chemotherapy, although findings are controversial between different cancer types." (PMID 33042844, 2020). "Therefore, this represents an exciting advance in the search for a targeted, novel therapy for PDAC and other S100P-expressing cancers." (PMID 32707527, 2020). "S100P is a member of the large family of S100 calcium-binding proteins that mediate Ca2+-dependent signal transduction pathways, and elevated levels of S100P have been described in a variety of human cancers." (PMID 32596149, 2020). "S100P was found to contribute to a cancer pathway dependent on the context of E-cadherin function." (PMID 31767037, 2019). "Importantly, in cancer cells with dysfunctional E-cadherin, S100P activates a distinct signaling pathway and its expression worsens the global effects mediated by loss of E-cadherin." (PMID 31767037, 2019). "Given the well-established role for S100P in promoting cancer cell invasion, we assessed whether S100P could regulate the invasiveness of Jeg-3 and Bewo cells." (PMID 30065265, 2018). "In contrast, S100P staining occurred in the nucleus and cytoplasm of cancer cells in CCA tissues." (PMID 30402042, 2018). "So far, S100P is reported to be involved in the development and progression of various cancers." (PMID 25688367, 2015). "Overexpression of S100P has been detected in several types of cancers." (PMID 26009899, 2015). "S100P, a Ca2+ binding protein, has been shown to be overexpressed in various cancers." (PMID 26320193, 2015). "S100P-mediated RAGE receptor activation has been demonstrated to be a critical step in the overall pathway for the subsequent downstream stimulation of cell proliferation in various cancer cell lines." (PMID 25084534, 2014). "Our results suggest that pentamidine may represent a potential drug for the treatment of cancer by disrupting the interaction between S100P and the V domain of RAGE." (PMID 25084534, 2014). "The binding of calcium-bound S100P to RAGE activates downstream signaling cascades in cancer cells." (PMID 25084534, 2014). "Thus, S100P contributes to cancer progression by promoting cell proliferation, cell survival, angiogenesis, and metastasis." (PMID 23785431, 2013). "The expression ratio of S100P in cancer/normal cells was high in AD samples and low in SQ samples." (PMID 20142997, 2010).
cancer (continued). "All these results clearly demonstrated that the 18-9 MAb is specific for S100P protein and approved its use for the immunohistochemical analysis of S100P expression in human tissues and carcinomas including breast, gastric, pancreatic, ovarian, prostate, and colon tumors." (PMID 18282279, 2008). "Consequently, we may have overlooked potential associations between S100P/S100A8 and other cancers, particularly those with smaller sample sizes." (PMID 40224483, 2025). "How the presence S100P in the extracellular/membrane bound fraction is responsible for promoting these effects is currently not known but appears not to plays a role in focal adhesion changes that are seen when high levels of S100P are expressed in trophoblast cells or in cancer cells." (PMID 37627296, 2023). "Therefore, blocking S100P might be a targeted intervention used to sensitize cancer cells to chemotherapy drugs and help in the treatment of CCa." (PMID 37927641, 2023). "Therefore, S100P is considered a potential therapeutic target and a marker for cancer patients." (PMID 37511575, 2023). "Given the well-established role for S100P in promoting cell invasion in both cancer cells and trophoblast cells, we next wanted to assess whether the extracellular/membrane bound S100P pool of proteins could regulate the invasiveness of Jeg-3 and HTR8/SVneo cells." (PMID 37627296, 2023). "In addition, several studies have shown that S100P plays an important role in cancer development." (PMID 34200172, 2021). "In addition, the association of S100P with the Siah 1 interacting protein (CacyBP/SIP) and calcyclin-binding protein resulted in β-catenin degradation, which is responsible for tumorigenesis in various cancer types." (PMID 33923162, 2021). "However, it was unclear if S100P is necessary for the functions of SOX9 in cancer progression." (PMID 26009899, 2015). "By contrast, cluster D3, which showed an enrichment for markers such as TFF1 and S100P, was primarily composed of PDAC samples, suggesting that this subset represents cancer cells." (PMID 39485038, 2024). "Significant differences were observed in the protein concentration levels of S100P, PIGR, C1QBP, TAGLN, and CNN1 between cancer and inflammatory lesions (P ═ 0.0006, P ═ 0.0032, P ═ 0.0008, P < 0.0001, P ═ 0.0094, respectively)." (PMID 39284282, 2024). "Thus, it is possible that some of the S100P detected may be present in the extracellular matrix since it has been shown to be secreted in this space via both autocrine and paracrine processes, at least in cancer cells." (PMID 37627296, 2023). "This heatmap, based on a dataset including samples from NILM, ASC-US, and ≥LSIL groups, displays two main clusters: cancer markers (MCM3, CEACAM5, S100P, ICAM1) on the left and healthy markers (CRNN, EVPL, DSC2) on the right side of the figure." (PMID 37445651, 2023). "We further validated the potential of the three identified genes, S100P, BPIFB1, and SLC6A14, as biomarkers for predicting the recurrence of early-stage cancer." (PMID 37152984, 2023). "A RAGE inhibitor derived from S100P can prevent the adherence of various RAGE ligands involved in inflammation and cancer." (PMID 36613714, 2022). "Cromolyn is a RAGE inhibitor that reduces cancer growth, endurance, and invasiveness in vitro by inhibiting RAGE interaction with S100P." (PMID 36613714, 2022). "We obtained the protein expression pattern of S100P and S100A2 in different cancers based on the HPA database." (PMID 35831362, 2022). "The interaction between S100P and RAGE specifically activates the nuclear factor-kappa B (NF-κB) signaling pathway, which increases resistance to therapeutic agents by promoting cancer cell survival and proliferation." (PMID 34200172, 2021).
cancer (continued). "Previous publications have shown that the degree of immunohistochemical staining of carcinoma cells for the proteins described, OPN, S100A4, S100P, AGR2 and FANCD2, reflect the level of each particular protein in the specimens." (PMID 27100728, 2016). "Previous studies strongly indicate that S100P can be secreted, acts through RAGE in an autocrine manner and plays a significant role in the development and progression of various cancers." (PMID 25084534, 2014). "Although S100P was reported to be expressed in various types of human cancer cells, including human HCC, the clinical and pathological significances of S100P expression in HCC remains largely unclear." (PMID 23785431, 2013). "Taxotere and Furtulon also up-regulated some genes (S-100P, ALDH1A3, casein kinase, annexin, etc) responsible for chemotherapeutic resistance, suggesting the induction of cancer cell resistance to these agents." (PMID 15656911, 2005). "Although both S100P and CTSE are highly expressed in pancreatic tissue, they predict different prognostic outcomes, suggesting distinct responses to cancer treatment that may ultimately affect patient survival." (PMID 41301873, 2025). "IL8, SAT, DUSP1, IL1b, HA3, S100P, and OAZ1, which are related to cancer." (PMID 38522008, 2024). "In all of these accounts, the presence of S100 proteins at the plasma membrane were primarily characterised in cancer cells but the presence of S100P in the plasma membrane of non-carcinogenic cells is yet unreported." (PMID 37627296, 2023). "Interestingly, the multifunctional, Ca++-binding S100A2 gene was one of few genes conserved in all 3 cohorts and S100P was conserved in the NEK and KRAS-mut cancers." (PMID 36612014, 2022). "We also observed that there was a negative correlation between miR-671 expression and S100P mRNA expression in PAAD cancer tissues." (PMID 33842379, 2021). "In our study, gene expression analyses show that S100A2, S100A11, and S100P expression levels in CRC tissues are significantly higher than those in noncancerous tissues, and S100A3 and S100A9 mRNAs are highly expressed in cancer tissues compared with normal tissue controls." (PMID 33294444, 2020). "CD44 variant isoforms including CD44v9 mitigate ROS, which may explain the high level of expression of CD44v9 in addition to S100P and COX-2 predominantly in the tissues of OV-CCA, a cancer driven by inflammation." (PMID 30402042, 2018). "Furthermore, AKT knockdown prevented S100P-mediated ZEB1 upregulation in CL1-0 cells, suggesting that the FAK/AKT/ZEB1 axis plays a role in S100P-mediated cancer EMT and migration." (PMID 26320193, 2015). "Extracellular S100P activates RAGE, which is a multiligand transmembrane receptor of the immunoglobulin super family, and it has been identified as a factor that influences the characteristics of various cancer cell types." (PMID 26009899, 2015). "XAGE-1, COL4A1, S100P and TM4SF1 were observed to show elevated expression in various cancers, but the expression level of these genes in HCC has not been reported previously." (PMID 19171046, 2009).
infection (4 papers, 2016 to 2025). The state of being infected such as from the introduction of a foreign agent such as serum, vaccine, antigenic substance or organism. "The expression of S100P was inhibited by more than 95% at both the mRNA and protein levels after infection with the S100P shRNA lentiviruses, and the cells infected with scrambled sequence showed no significant change in S100P levels." (PMID 32883230, 2020). "This population includes several neutrophil-associated genes (OLFM4, CD177, SERPINB1, S100P, PTX3 and MMP8), suggesting that there is an accumulation of neutrophils in PBCMs during the course of infection." (PMID 27595844, 2016).
adenocarcinoma (3 papers, 2015 to 2023). A common cancer characterized by the presence of malignant glandular cells. "However, the expression of S100P in adenocarcinoma-derived Ishikawa cells was also much higher than that in normal endometrial epithelial and stromal cells." (PMID 32883230, 2020).
gastrointestinal tract cancers (1 paper, 2021). "When stratified by anatomic structure, S100P overexpression was associated with poor prognosis in non-gastrointestinal tract cancers (HR=1.98, 95% CI: 1.44-2.72, P<0.001) but not in gastrointestinal tract cancers (HR=1.09, 95% CI: 0.66-1.81, P=0.727)." (PMID 33747914, 2021).
S100P also shares sentences with these, for which no sentence is quoted: pancreatic ductal adenocarcinoma (5 papers); invasive carcinoma (3); acute coronary syndrome (2); breast tumors (2); peripheral neuropathy (2); pneumonia (2); adenoid cystic carcinoma (1); alcohol abuse (1); Ataxia (1); bacterial infection (1); breast fibroadenoma (1); chondrosarcoma (1); chronic pancreatitis (1); clear cell adenocarcinoma of the ovary (1); colon adenocarcinoma (1); diffuse large B-cell lymphoma (1); Dystonia (1); endometrial adenosquamous carcinoma (1); epithelial dysplasia (1); gallbladder adenocarcinoma (1); inflammation (1); invasive urothelial carcinoma of the bladder (1); lipoma (1); liver cirrhosis (1); liver fibrosis (1); metastatic prostate carcinoma (1); myasthenia gravis (1); neurodegenerative disease (1); oligodendroglioma (1); osteosarcoma (1).
A further 13 diseases each share a sentence with S100P in 1 paper.